ARSJ (arylsulfatase family member J)
Synonyms: ASJ; FLJ23548
Tractability: Antibody: UniProt places it where antibodies can reach, with high confidence; UniProt predicts a signal peptide or a membrane-spanning region; its Gene Ontology location is reachable by antibodies, with medium confidence.
Gene: Protein-coding gene on chromosome 4 (113,900,284 to 113,979,727, reverse strand). Ensembl gene ENSG00000180801.
Subcellular location: Secreted
Subcellular location (Human Protein Atlas): Actin filaments; Predicted to be secreted
Pathways (Reactome):
Metabolism: Glycosphingolipid catabolism
Metabolism of proteins: The activation of arylsulfatases
Gene Ontology:
Molecular function: arylsulfatase activity; sulfuric ester hydrolase activity
Cellular component: actin cytoskeleton; endoplasmic reticulum lumen; extracellular region
Genetic constraint (gnomAD): Loss-of-function variants: 32 observed, 45.21 expected, observed/expected ratio (o/e) 0.71, 90% interval 0.53 to 0.95. The upper end of that interval is the gene's LOEUF score, 0.95, which puts it in group 4 of 6, group 1 being the genes least tolerant of losing a copy. Missense variants: 667 observed, 765.95 expected, observed/expected ratio (o/e) 0.87, 90% interval 0.82 to 0.93. Synonymous variants: 294 observed, 284.96 expected, observed/expected ratio (o/e) 1.03, 90% interval 0.94 to 1.14.
Homologues: Orthologues: chimpanzee ARSJ (99% identical), macaque ARSJ (97% identical), dog ARSJ (92% identical), pig ARSJ (92% identical), rat Arsj (90% identical), mouse Arsj (89% identical), guinea pig ARSJ (74% identical), tropical clawed frog arsj (73% identical), zebrafish arsj (64% identical), Drosophila melanogaster CG7402 (26% identical), Drosophila melanogaster CG7408 (23% identical), Drosophila melanogaster CG32191 (23% identical), and 5 more. Paralogues in human: ARSI (57% identical), ARSB (45% identical), STS (23% identical), ARSL (23% identical), ARSD (22% identical), GALNS (22% identical), ARSF (22% identical), ARSH (20% identical), ARSG (20% identical), ARSA (20% identical), SULF2 (19% identical), IDS (18% identical), and 4 more.
Diseases named in the same sentence as ARSJ in open-access papers:
ARSJ is named in the same sentence as 8 diseases in open-access papers, as found by Europe PMC text mining. Sharing a sentence is not in itself a finding about the gene and the disease. The quoted sentences say what the papers report.
cancer (3 papers, 2019 to 2024). A tumor composed of atypical neoplastic, often pleomorphic cells that invade other tissues. "Most of these genes, such as CDIPT, PIK3C2G, ARSJ, ARSE, GLA and GLB2, had not been studied in cancers." (PMID 31475440, 2019).
ARSJ also shares sentences with these, for which no sentence is quoted: colorectal cancer (1 paper); Fanconi anemia (1); hepatocellular carcinoma (1); metabolic disorders (1); neurological diseases (1); ovarian carcinoma (1); theileriasis (1).